RFC4 (replication factor C subunit 4)
Diseases named in the same sentence as RFC4 in open-access papers (continued):
Sharing a sentence is not in itself a finding about the gene and the disease.
nasopharyngeal carcinoma (2 papers, 2024 to 2025). A carcinoma arising from the nasopharyngeal epithelium. "Additionally, RFC4 knockout can induce G2/M cell cycle arrest and inhibit nasopharyngeal carcinoma cell proliferation." (PMID 39031628, 2024). "Replication factor C subunit 4 (RFC4) facilitates the progression of nasopharyngeal carcinoma (NPC) through the modulation of HOXA10, which in turn promotes cellular proliferation and tumor growth." (PMID 40980067, 2025).
basal cell carcinoma (1 paper, 2024). A carcinoma involving the basal cells. "UMAP plots revealed the expression of RFC4 in T cell, B cell and macrophages in basal cell carcinoma (BCC_GSE123813_aPD1), with particularly high levels of RFC4 expression observed in proliferating T cells (Tprolif) where particularly high expression was observed." (PMID 39031628, 2024).
dysferlinopathy (1 paper, 2023). "Analysis of muscle transcripts from patients with dysferlinopathy identified 6 downregulated DEGs (RFC4, RFC5, ATAD5, TP53BP1, WDR48, and RAD17) related to the cellular response to DNA damage stimulus." (PMID 38125829, 2023).
esophageal cancer (1 paper, 2021). A primary or metastatic malignant neoplasm involving the esophagus. "The results indicated that the expression of RFC4 was highly correlated with the expression of GMPS in esophageal carcinoma in TCGA data." (PMID 34520390, 2021). "Altogether, we concluded that the increase in RCF4 and GMPS may be mediated by DNA copy number alterations, and that the increased expression of RFC4 and GMPS was associated with an early tumor stage and early nodal metastatic status in esophageal carcinoma." (PMID 34520390, 2021). "In order to further explore the expression of RFC4 and GMPS in the esophageal carcinoma, the Oncomine dataset was used." (PMID 34520390, 2021). "To further explore the reason for the increased RFC4 and GMPS in ESCC, we first explored genetic alterations in RFC4 and GMPS in esophageal carcinoma by a cBioPortal analysis." (PMID 34520390, 2021). "Among the most significant DEGs, RFC4 and GMPS were both increased in the early stage and early nodal metastases of esophageal carcinoma." (PMID 34520390, 2021). "Furthermore, the discovery of RFC4 and GMPS can help us better understand the early diagnosis and treatment of esophageal cancer." (PMID 34520390, 2021). "In future, RFC4 and GMPS may serve as the targets for immunotherapy of esophageal cancer and improve the treatment of esophageal cancer." (PMID 34520390, 2021). "The function of RFC4 and GMPS in esophageal cancer were highly consistent." (PMID 34520390, 2021). "In addition, RFC4 and GMPS perform the similar functions, and the expression of RFC4 was highly correlated with the expression of GMPS in esophageal cancer." (PMID 34520390, 2021). "Therefore, we reasonably concluded that RFC4 and GMPS involved in the immune regulation of esophageal cancer." (PMID 34520390, 2021). "In summary, we speculate that RFC4 and GMPS overexpression might influence tumor immune responses in the tumor microenvironment and that they may play a crucial role in esophageal carcinoma progression." (PMID 34520390, 2021). "Therefore, we inferred that DNA copy number alterations mediated the increase in RFC4 and GMPS in the early stage of esophageal carcinoma." (PMID 34520390, 2021). "Therefore, we investigated the relationship between RFC4 and GMPS expression and immune infiltration in esophageal carcinoma using the online tool TIMER." (PMID 34520390, 2021). "Furthermore, RFC4 and GMPS were both upregulated in the early stage and early nodal metastases of esophageal carcinoma." (PMID 34520390, 2021). "Therefore, we inferred that the levels of RFC4 and GMPS may be mediated by an increased DNA copy number and related to the occurrence of esophageal cancer." (PMID 34520390, 2021). "Therefore, we hypothesize that RFC4 and GMPS are involved in the early progression of esophageal cancer, and mediate the immune escape of esophageal carcinoma." (PMID 34520390, 2021). "A high expression of RFC4 and GMPS could mediate immune escape from esophageal cancer." (PMID 34520390, 2021). "Finally, we concluded that RFC4 and GMPS are significant for the early diagnosis of esophageal carcinoma and that they may participate in the tumor immune response." (PMID 34520390, 2021).
leiomyosarcoma (1 paper, 2022). An uncommon, aggressive malignant smooth muscle neoplasm, usually occurring in post-menopausal women. "In Barretina Sarcoma’s dataset, RFC4 was overexpressed in Leiomyosarcoma with a fold change of 7.827." (PMID 35483337, 2022).
liposarcoma (1 paper, 2022). A usually painless malignant tumor that arises from adipose tissue. "Barretina Sarcoma’s dataset also indicated that RFC4 overexpression is found in Pleomorphic Liposarcoma with a fold change of 4.682." (PMID 35483337, 2022). "RFC4 over-expression was found in Myxofibrosarcoma with a fold change of 4.518, in Myxoid/Round Cell Liposarcoma with a change of 3.952, and in Dedifferentiated Liposarcoma with a change of 3.099." (PMID 35483337, 2022).
metastatic melanoma (1 paper, 2022). A melanoma that has spread from its primary site to another anatomic site. "Notably, the top 20 genes from topological analysis algorithms included four hub genes: CDK1, FOXM1, KIF11, and RFC4, which may involve in the development of metastatic melanoma." (PMID 35906389, 2022).
oral squamous cell carcinoma (1 paper, 2025). "We evaluated the expression pattern and function of replication factor C subunit 4 (RFC4) and its potential as a prognostic and predictive biomarker in oral squamous cell carcinoma (OSCC) through bioinformatics analysis." (PMID 39673181, 2025).
Pca (1 paper, 2023). "By combining both KEGG analysis and GO term analysis, seven genes (RNASEH2A, RFC2, RFC4, LIG1, POLD1, POLD2, and POLE4) were identified as new biomarker genes upregulated in CRPC compared to localized Pca and associated with DNA replication and DNA repair." (PMID 37950047, 2023). "We identified six DDR-related genes (Ribonuclease H2 Subunit A (RNASEH2A), replication factor C subunit 2 (RFC2), RFC4, DNA Ligase 1 (LIG1), DNA polymerase D1 (POLD1), and DNA polymerase E4 (POLE4)) that were upregulated in CRPC compared with Pca tissues." (PMID 37950047, 2023).
rectal cancer (1 paper, 2024). A primary or metastatic malignant neoplasm that affects the rectum. "Furthermore, previous research has shown that the RFC4 expression level may serve as a prognostic indicator for the efficacy of radiation and the overall prognosis of neoadjuvant radiation therapy in individuals diagnosed with locally advanced rectal cancer." (PMID 38399367, 2024).
sarcoma (1 paper, 2022). A usually aggressive malignant neoplasm of the soft tissue or bone. "At the same time, highly expressed RFC4 was related to the RFS difference in sarcoma, and there was statistical significance, that is, the DFS of sarcoma patients with high expression of RFC4 was worse." (PMID 35483337, 2022). "The results, however, of the database suggested that high expression of RFC2 and RFC4 were associated with the poor DFS and RFS in sarcoma, with statistical differences." (PMID 35483337, 2022). "It seemed that RFC4 not only acted as an oncogene in sarcoma patients but also had a certain predictive effect on the prognosis of sarcoma patients." (PMID 35483337, 2022). "The results showed that RFC2, RFC4, and RFC5 were upregulated in sarcoma patients, while the high expression levels of RFC1 and RFC3 were both with no significance." (PMID 35483337, 2022). "In general, RFC4 has been discussed and studied in various cancers, but its exact function in sarcoma has not been described yet." (PMID 35483337, 2022). "In addition, Cancer Cell Line Encyclopedia (CCLE) dataset analysis indicated that RFC1, RFC2, RFC3, RFC4, and RFC5 were elevated expressed in sarcoma cell lines." (PMID 35483337, 2022). "Similarly, we found that mRNA expression levels of RFC2, RFC3, RFC4, and RFC5 from RFC family genes were upregulated in sarcoma tissues." (PMID 35483337, 2022).
tumor (31 papers, 2008 to 2025). "The comparative analysis of the two databases showed significant findings on the association between the RFC4 level and tumor stage in five distinct types of malignancies, particularly ACC, KICH, KIRC, KIRP, and LIHC." (PMID 38399367, 2024). "This suggests that the mechanism of tumour occurrence can be explored and diagnostic predictions can be made based on the alternative splicing of RFC4." (PMID 39031628, 2024). "Our findings show that RFC4 is upregulated in several tumor types and associated with poor prognoses in many human cancers." (PMID 38399367, 2024). "The present work utilized the “compare tumor, normal, and metastasis” module of the TNMplot web server to investigate the association between RFC4 mRNA expression levels and cancer occurrence and spread." (PMID 38399367, 2024). "Replication Factor C Subunit 4 (RFC4), an oncogene implicated in many human cancers, has yet to be extensively studied in many cancer types to determine its expression patterns and tumor tissue function." (PMID 38399367, 2024). "Downregulated RFC4 inhibits tumour proliferation by causing S‐phase arrest and inhibiting mitosis, resulting in the reduction of tumour cells." (PMID 39031628, 2024). "On the contrary, a negative connection was observed for NKT cells in 10 of the examined tumors, except for the LIHC tumor, where there was a positive association between RFC4 and the number of NKT cells." (PMID 38399367, 2024). "The TISIDB web server data examination revealed a significant association between RFC4 expression and the tumor grade in HNSC, KIRC, LGG, LIHC, PAAD, and UCEC (p < 0.001)." (PMID 38399367, 2024). "A previous study demonstrated that RFC4 is overexpressed in CRC and is associated with tumor progression and poor survival results, which is consistent with the results found in this study that RFC4 was jointly up-regulated in the five datasets." (PMID 34120619, 2021). "High levels of RFC4, determined on a tissue microarray, were significantly associated with differentiation, an advanced stage by the Tumor-Node-Metastasis (TNM) staging system, and a poor prognosis, as compared to low levels of expression (P <0.05)." (PMID 25407051, 2014). "The group was headed by MCM2, ECT2, and RFC4, which are associated with DNA replication, DNA repair or positive regulation of signal transduction, indicating that these genes are essential for tumor growth." (PMID 24879114, 2014). "The current study showed that RFC4 is overexpressed in CRC and that increased RFC4 expression is significantly associated with poorly differentiated and advanced tumor TNM stage." (PMID 25407051, 2014). "This overexpression of RFC4 has been linked to tumor advancement and unfavorable survival rates." (PMID 38399367, 2024). "Third, our results showed that RFC4 expression was positively correlated with tumor purity, and negatively correlated with stromal, immune and ESTIMATE scores." (PMID 40458559, 2025). "Based on clinical characteristics such as age and tumor differentiation, we found that high RFC4 expression was stable in different subgroups of patients with CC, indicating that differential expression of RFC4 is reliable." (PMID 40458559, 2025). "In the present study, we scrutinized the increased infiltration of activated dendritic cells and decreased infiltration of macrophage M0 cells in the tumor tissues of OSCC patients with high RFC4 expression." (PMID 39673181, 2025). "In vivo tumor formation assays demonstrated that RFC4 knockdown resulted in a significant decrease in tumor growth and expression of Ki‐67 expression in mice." (PMID 39673181, 2025). "The IHC assay further confirmed that expression of RFC4 was significantly up‐regulates in OSCC tumor tissues compared to that in normal tissues (P < 0.0001), which is consistent with the results of the data analysis." (PMID 39673181, 2025).
tumor (continued). "We identified six signature LRGs (ALB, G6PD, HMGA1, MKI67, RACGAP1, and RFC4) possess prognostic potential, correlation with immune infiltration, and lactylation-related pathways, providing novel insights into tumor microenvironment (TME) of HCC." (PMID 40421085, 2025). "This protein has been found to be negatively correlated with tumor prognosis; patients with poor prognosis had significantly higher RFC4 expression levels than those with good prognosis." (PMID 41463494, 2025). "The expression levels of G6PD, HMGA1, MKI67, RACGAP1, and RFC4, were significantly higher in tumor samples with (p < 0.05)." (PMID 40421085, 2025). "The evidence from HCC samples suggests that elevated levels of RFC4 in tumour tissue are related to tumour growth and prognosis, which is consistent with our research findings." (PMID 39031628, 2024). "Cell experiments have shown that downregulated RFC4 can inhibit cell cycle and tumour cell proliferation." (PMID 39031628, 2024). "To further investigate the expression of RFC4 in various cell types of tumour tissues, we analysed the single‐cell expression of RFC4 used 40 datasets from the TISCH database." (PMID 39031628, 2024). "We used the SpliceSeq module from the OncoSplitting database to investigate the expression and prognostic value of three variable splices of RFC4 in tumours." (PMID 39031628, 2024). "The results showed that the methylation level of RFC4 was negatively correlated with the expression of RFC4 in tumours such as BLCA, BRCA, LIHC, LUAD and STAD (p < 0.05)." (PMID 39031628, 2024). "We first examined RFC4 expression levels in several human tumor types to determine relationships with tumor grade, stage, metastasis, and patient survival." (PMID 38399367, 2024). "Our analysis of single‐cell sequencing data from different tumours revealed that RFC4 is highly expressed in Tprolif cells and tumour cells." (PMID 39031628, 2024). "In summary, higher RFC4 expression was strongly associated with and LIHC, COAD and KIRC tumour prognosis." (PMID 39031628, 2024). "In the remaining four tumour treatments, RFC4 expression was also upregulated to varying degrees in responders, and the BI‐2536 treatment OS of AUC values all exceeded 0.6." (PMID 39031628, 2024). "In our study, we scrutinized the molecular interactions of RFC4, a protein demonstrating significant influence on clinical outcomes, tumor stages, grades, and immune cell infiltration in various cancers." (PMID 38399367, 2024). "The findings of this study indicate a significant increase in RFC4 protein expression in tumor tissues of the colon, HNSC, clear cell RCC, HCC, LUAD, and OV compared to normal tissues." (PMID 38399367, 2024). "Herein, we revealed that RFC4 is more consistently overexpressed in tumor tissues than in normal tissues." (PMID 38399367, 2024). "This study performed a comprehensive multi-omics analysis to delineate RFC4 involvement in tumor progression." (PMID 38399367, 2024). "The level of RFC4 expression was found to be directly proportional to the resistance of anti‐tumour drugs such as vinorelbine." (PMID 39031628, 2024). "To investigate the relationship between the up-regulation of RFC4 in tumor tissue and potential biomarkers, we conducted an analysis to determine if a correlation exists." (PMID 38399367, 2024). "The methylation level and variable splicing level of RFC4 were abnormal in most tumours compared with the adjacent tissues." (PMID 39031628, 2024). "We investigated the expression and prognostic levels of DNA methylation of RFC4 in tumours using the DNMIVD database." (PMID 39031628, 2024). "Once again, it was observed that there was a consistent trend of increased RFC4 expression in tumor tissues across various types of cancers, including COAD, HNSC, clear cell RCC, HCC, LUAD, and OV." (PMID 38399367, 2024).
tumor (continued). "Prospective studies that focus on RFC4 expression and the tumour immune environment will help provide conclusive answers, facilitating the development of immune‐based anti‐cancer therapies in the future." (PMID 39031628, 2024). "Our findings indicated that KIRC, LIHC, and UCEC exhibited an escalation in both tumor stage and grade in conjunction with RFC4 expression." (PMID 38399367, 2024). "Further analysis revealed that a high expression of RFC4 also indicates poor prognosis, even when accompanied by high levels of tumor-infiltrating immune cells, including CD4+ T cells, CD8+ T cells, B cells, dendritic cells and monocytes." (PMID 34520390, 2021). "We uncovered that a high expression of RFC4 and GMPS accompanied by high levels of tumor-infiltrating immune cells was associated with a poor prognosis." (PMID 34520390, 2021). "RFC4 is frequently overexpressed in CRC, and is associated with tumor progression and worse survival outcome." (PMID 25407051, 2014). "The expression of replication factor C complex (RFC2, RFC3 and RFC4) is indicative of proliferative potential (high cell division rates) of BRCA1 tumours." (PMID 25521701, 2014). "DNA synthesis in RFC4 knockdown tumor cells was significantly inhibited as compared to that in control tumor cells (P <0.05)." (PMID 25407051, 2014). "However, patients with high RFC4 expression in CC have a better prognosis, possibly because RFC4 exerts antitumor effects by affecting the immunostimulatory tumor microenvironment, such as immunostimulatory and dendritic cell infiltration." (PMID 40458559, 2025). "This suggests that downregulation of RFC4 suppresses OSCC tumor growth in vivo." (PMID 39673181, 2025). "In the future, silencing (shRNA/CRISPR) or overexpression of RFC4 in LUAD cell lines could be used to examine its impact on tumor growth, immune evasion, drug sensitivity, and cytokine expression." (PMID 40612960, 2025). "Further research has found that abnormal RFC4 expression may regulate the tumor microenvironment by altering the status of infiltrating immune cells within the tumor tissues." (PMID 40458559, 2025). "Unfortunately, we did not observe any correlation between RFC4 expression levels and tumor staging, nor were they associated with clinical features such as gender, age, and smoking status." (PMID 40612960, 2025). "Previous studies have identified the role of RFC4 in cell proliferation and tumor formation, and its abnormal expression may serve as a significant prognostic indicator for various types of cancer." (PMID 39673181, 2025). "This study aimed to determine whether RFC4 overexpression affects overall survival in CC and to explore its impact and potential mechanisms on the tumor immune microenvironment." (PMID 40458559, 2025). "Based on the results of three algorithms, TIMER, MCPCOUNTER and CIBERSORT, we found a significant correlation between the expression level of RFC4 in tumours such as KIRC, LUAD and LIHC and the infiltration degree of CD4 + T cells, CD8 + T cells, B cells, macrophages and dendritic cells." (PMID 39031628, 2024). "This suggests that RFC4 may activate T cells to inhibit tumour growth, while also being an essential gene for tumour cell growth." (PMID 39031628, 2024). "Through pan‐cancer analysis, we found that RFC4 is significantly upregulated in most tumours." (PMID 39031628, 2024). "Additionally, RFC4 is involved in microtubule‐binding and histone enzyme activity, both of which play crucial roles in tumour growth." (PMID 39031628, 2024). "The tumour patients with high expression of RFC4 have poor prognosis." (PMID 39031628, 2024). "Furthermore, it was observed that a positive link existed between the expression of RFC4 and tumor metastasis in various organs, including breast, kidney, liver, lung, pancreas, and prostate." (PMID 38399367, 2024). "Furthermore, the expression levels of RFC4 in normal liver and tumour tissues were analysed, along with its impact on the prognosis of HCC." (PMID 39031628, 2024).